ZFP36 (ZFP36 zinc finger CCCH-type)
Diseases named in the same sentence as ZFP36 in open-access papers (continued):
Sharing a sentence is not in itself a finding about the gene and the disease.
bacterial pneumonia (1 paper, 2014). Acute infection of the lung parenchyma caused by bacteria (e.g., Streptococcus pneumoniae, Haemophilus influenzae, Chlamydia pneumoniae, Mycoplasma pneumoniae, and Legionella pneumophila). "In conclusion, these results imply that myeloid ZFP36 may fully compensate for loss of ZFP36L1 or that Zfp36l1-dependent mRNA expression does not play an integral role in the host defense against bacterial pneumonia." (PMID 25299049, 2014).
brucellosis (1 paper, 2024). Brucellosis is a bacterial infection that spreads from animals to people via unpasteurized dairy products or by exposure to contaminated animal products or infected animals. "Interestingly, a series of commonly upregulated genes were identified in brucellosis patients, with seven genes/transcription factors (RGS1, DUSP1, FOS, PPP1R15A, TNFAIP3, HLA‐E, and ZFP36) being the most frequent (nine times among nine clusters)." (PMID 39135683, 2024).
Burkitt lymphoma (1 paper, 2014). A rare form of malignant mature B-cell non-Hodgkin lymphoma. "In Eμ-Myc mice, a mouse model of human Burkitt lymphoma, and also in human Burkitt lymphoma versus non-Burkitt lymphomas, ZFP36 and ZFP36L1 were shown to be transcriptionally repressed." (PMID 25014217, 2014).
cardiac hypertrophy (1 paper, 2025). "The underlying mechanisms governing the alteration of Zfp36 expression in cardiomyocytes during myocardial hypertrophy have yet to be elucidated, presenting an ongoing challenge for clinical application." (PMID 40000392, 2025). "Zinc finger protein 36 (Zfp36) is recognised as a critical regulator of ferroptosis; however, its role and underlying mechanisms in cardiac hypertrophy remain largely unexplored." (PMID 40000392, 2025). "Single‐cell sequencing analysis demonstrated a reduction in Zfp36 expression associated with cardiac hypertrophy." (PMID 40000392, 2025). "Collectively, these findings underscore the involvement of Zfp36 in cardiovascular diseases; however, its role and underlying molecular mechanisms in relation to ferroptosis in cardiac hypertrophy remain unexplored." (PMID 40000392, 2025). "Cardiac‐specific overexpression of Zfp36 mitigated cardiac hypertrophy by inhibiting ferroptosis, whereas Zfp36 deficiency aggravated cardiac hypertrophy by promoting ferroptosis." (PMID 40000392, 2025). "Moreover, Zfp36 has been associated with the inhibition of ferroptosis in various diseases, although its precise role in ferroptosis‐mediated cardiac hypertrophy requires further exploration." (PMID 40000392, 2025). "This study provides compelling evidence, for the first time, that Zfp36 is integral in suppressing ferroptosis and reducing cardiac hypertrophy through the Ythdc2/SLC7A11/GSH axis in cardiomyocytes (Graphical Abstract)." (PMID 40000392, 2025). "The data reveals the critical role of Zfp36, a protein responsive to stress conditions, in modulating the outcomes of cardiac hypertrophy." (PMID 40000392, 2025). "The primary discovery of our study is the regulatory role of Zfp36 in ferroptosis within the context of cardiac hypertrophy." (PMID 40000392, 2025). "Initial investigations associated with hematopoietic alterations and the suppression of inflammation changes in Zfp36 expression in early‐stage myocardial hypertrophy models." (PMID 40000392, 2025). "Together, these findings indicate that Zfp36 modulates cardiac hypertrophy and ferroptosis through its interaction with Ythdc2." (PMID 40000392, 2025). "Collectively, these findings suggest that Zfp36 overexpression alleviates cardiac hypertrophy through the inhibition of ferroptosis." (PMID 40000392, 2025). "This study elucidates the role of Zfp36 in cardiac hypertrophy, specifically detailing its modulatory mechanism via the Ythdc2/SLC7A11/GSH ferroptosis pathway." (PMID 40000392, 2025). "This study aims to investigate the regulatory function of Zfp36 in ferroptosis within the context of cardiac hypertrophy." (PMID 40000392, 2025). "Collectively, these findings highlight the role of Zfp36 in modulating cardiac hypertrophy via the Ythdc2/SLC7A11/GSH‐dependent ferroptosis pathway." (PMID 40000392, 2025). "In this investigation, multiple lines of evidence were generated to clarify the function of Zfp36 in ferroptosis and cardiac hypertrophy." (PMID 40000392, 2025). "The initial findings indicated that Zfp36 is involved in mitigating ferroptosis during cardiac hypertrophy by targeting Ythdc2." (PMID 40000392, 2025). "Successful knockout of Zfp36 was confirmed, allowing us to assess whether the siRNA‐mediated promotion of ferroptosis and exacerbation of myocardial hypertrophy under Ang II conditions could be replicated." (PMID 40000392, 2025). "Our findings reveal that Zfp36 ameliorates cardiac hypertrophy by inhibiting ferroptosis." (PMID 40000392, 2025). "The findings of this study collectively indicate that targeting Zfp36 may represent a viable therapeutic strategy to prevent the transition from cardiac hypertrophy to heart failure." (PMID 40000392, 2025). "In this study, we observed a reduction in Zfp36 levels during cardiac hypertrophy." (PMID 40000392, 2025). "Initially, bioinformatics analyses of single‐cell and RNA‐seq revealed that Zfp36 may inhibit ferroptosis during the cardiac hypertrophy process." (PMID 40000392, 2025).
cardiac hypertrophy (continued). "Moreover, we demonstrate that the overexpression of Zfp36 significantly mitigates cardiac hypertrophy induced by Ang II and TAC by alleviating ferroptosis, whereas the knockdown exacerbates these pathological conditions." (PMID 40000392, 2025). "This section examines the targets of Zfp36 during cardiac hypertrophy." (PMID 40000392, 2025). "Furthermore, the expression levels of Zfp36 protein were observed to be downregulated in hypertrophic conditions, proposing that Zfp36 may be engaged in the ferroptosis process during cardiac hypertrophy." (PMID 40000392, 2025). "Furthermore, Zfp36 overexpression led to an increase in GSH levels; however, this effect was negated by concurrent Ythdc2 overexpression in the context of cardiac hypertrophy." (PMID 40000392, 2025).
chronic kidney disease (1 paper, 2023). Impairment of the renal function secondary to chronic kidney damage persisting for three or more months. "In this study, we investigated the potential of EGF, ZFP36, and PAG1 as biomarkers for chronic kidney disease (CKD)." (PMID 37988198, 2023).
colitis (1 paper, 2023). Inflammation of the colon. "Consistently, conditional knockout of Zfp36 gene in macrophages ameliorated colitis development in a DSS‐induced animal model." (PMID 36922750, 2023).
disc degeneration (1 paper, 2022). "However, no study was found describing how ZFP36 relates to disc degeneration." (PMID 36531954, 2022).
emphysema (1 paper, 2025). "In a cigarette-induced COPD mouse model, ZFP36 was found to decrease emphysema, airway remodeling, and impairment of lung function." (PMID 40811488, 2025).
endotoxemia (1 paper, 2015). "Tissue-specific deletion of the Zfp36 gene in myeloid cells rendered mice extremely sensitive to LPS-induced endotoxemia." (PMID 26002976, 2015).
Glucose intolerance (1 paper, 2026). Glucose intolerance (GI) can be defined as dysglycemia that comprises both prediabetes and diabetes. "Functionally, mice lacking ZFP36 specifically in adipose tissue (ZFP36^AKO) and fed a high-fat diet for 16 weeks gained more weight and exhibited pronounced glucose intolerance and insulin resistance compared with controls." (PMID 41596407, 2026).
gout (1 paper, 2023). A condition characterized by painful swelling of the joints, which is caused by deposition of urate crystals. "The CD4+ TCs and CD8+ TCs from gout remission were enriched in chemokines, such as CXCR4, as well as various antiinflammatory regulators (TNFAIP3, ZFP36, and SMAD7; an antagonist of TGF-β signaling)." (PMID 38063198, 2023).
HCMV infection (1 paper, 2023). "Interestingly, HCMV infection does not induce but rather represses ZFP36 expression to maintain high levels of IL-10 transcription and secretion." (PMID 37830871, 2023).
Hepatic steatosis (1 paper, 2026). Steatosis is a term used to denote lipid accumulation within hepatocytes. "Hepatocyte-specific Zfp36 knockdown exacerbates high-fat diet-induced liver injury and impairs the therapeutic effect of SG on hepatic steatosis." (PMID 42123322, 2026).
herpesvirus infection (1 paper, 2022). "The other significant pathways are Kaposi’s sarcoma-associated herpesvirus infection (steered by ZFP36 and CXCL2), PI3K-Akt signaling pathway and the proteoglycans in cancer pathways (steered by IGF2 and TLR2)." (PMID 35277538, 2022). "The pathway category Kaposi sarcoma-associated herpesvirus infection was enriched by two hub-DEGs (ZFP36 and CXCL2)." (PMID 35277538, 2022).
hypertrophic cardiomyopathy (1 paper, 2022). A condition in which the myocardium is hypertrophied without an obvious cause. "Finally, ZFP36 was associated with cytokine-cytokine receptor interactions, glycosphingolipid biosynthesis (lacto and neolecto series), hypertrophic cardiomyopathy, and pathways in cancer." (PMID 35372438, 2022).
Infertility (1 paper, 2024). "Collectively, our results demonstrate that the miR-29ab1/Zfp36/AR axis in the hypothalamus plays a pivotal role in the regulation of aggression and mating in male mice, providing a potential therapeutic target for treating infertility caused by low libido." (PMID 39684798, 2024).
influenza (1 paper, 2022). An acute viral infection of the respiratory tract, occurring in isolated cases, in epidemics, or in pandemics; it is caused by serologically different strains of viruses (influenzaviruses) designated A, B, and C, has a 3-day incubation period, and usually lasts for 3 to 10 days. "Finally, while our data suggests that ZFP36 and ZFP36L1 are redundant in limiting T cell dependent resilience to influenza, different outcomes for the individual RBP might be found upon other immune challenges such as persistent infection." (PMID 35477960, 2022).
Insulin resistance (1 paper, 2026). Increased resistance towards insulin, that is, diminished effectiveness of insulin in reducing blood glucose levels. "Polymorphisms in ZFP36 are associated with insulin resistance and dyslipidemia in obese individuals, suggesting a fundamental link between its function and metabolic health." (PMID 41596407, 2026). "Women with higher ZFP36 expression demonstrated improved insulin sensitivity, marked by lower fasting insulin, reduced insulin resistance (HOMA-IR), and lower insulin after glucose intake." (PMID 41596407, 2026).
iron overload (1 paper, 2023). "We conclude that JUN and ZFP36 could be the potential target genes to attenuate iron overload in patients with OA." (PMID 37741987, 2023).
ischaemic stroke (1 paper, 2022). "Eight hub genes (ADM, ANXA3, CARD6, CPQ, SLC22A4, UBE2S, VIM and ZFP36) were revealed to be significantly correlated with ischaemic stroke by a LASSO logistic regression and SVM-RFE machine learning methods." (PMID 35962388, 2022). "Eight hub genes (ADM, ANXA3, CARD6, CPQ, SLC22A4, UBE2S, VIM and ZFP36) were revealed to be significantly correlated with ischaemic stroke by the LASSO logistic regression and SVM-RFE algorithm." (PMID 35962388, 2022). "However, the expression levels of the CARD6, CPQ, UBE2S and ZFP36 genes did not significantly differ between the ischaemic stroke patients and normal subjects." (PMID 35962388, 2022). "However, the expression levels of the UBE2S and ZFP36 genes did not significantly differ between the ischaemic stroke patients and normal subjects in the testing set." (PMID 35962388, 2022).
ischemia (1 paper, 2021). A hypoperfusion of the BLOOD through an organ or tissue caused by a PATHOLOGIC CONSTRICTION or obstruction of its BLOOD VESSELS, or an absence of BLOOD CIRCULATION. "To study the involvement of ZFP36 in I/R-induced acute lung injury we first created an intestine ischemia model with reperfusion in C57BL/6 mice." (PMID 34238924, 2021).
liver cancer (1 paper, 2023). An epithelial or non-epithelial malignant neoplasm that arises from the liver. "The varied expression levels of DEFRGs between the tumor and control groups in the TCGA-LIHC liver cancer dataset were compared, where ZFP36, NCOA4, FTH1, FTL, TNF, and PCBP1 were matched with the TCGA transcriptome data." (PMID 37555866, 2023).
liver failure (1 paper, 2022). A liver disease characterized by the liver losing or has lost all of its function. "In summary, our research confirmed through animal experiments that ferroptosis-related genes Hmox1, Slc3a2, Jun and Zfp36 were significantly correlated with and highly expressed in liver failure." (PMID 35923893, 2022). "Finally, it was confirmed by the construction of septic liver failure mice model that ferroptosis-related genes of Hmox1, Slc3a2, Jun and Zfp36 were significantly correlated with liver failure and were highly expressed." (PMID 35923893, 2022). "Seven differentially expressed ferroptosis-related genes (Hmox1, Epas1, Sirt1, Slc3a2, Jun, Plin2 and Zfp36) were obtained through the intersection of ferroptosis-related genes in the FerrDb database with DEGs in the GSE60088 dataset, and all of these genes were up-regulated in liver failure." (PMID 35923893, 2022).
metastatic disease (1 paper, 2024). "We further documented in a meta-analysis of published data that localized PCa with ZFP36 RNA levels in the lower quartile was associated with an almost 2-fold risk of lethal PCa (metastatic disease or death from PCa) (bottom right)." (PMID 39560993, 2024).
mitral valve prolapse (1 paper, 2025). A fairly common and often benign valvular heart disorder characterized by redundancy or hooding of mitral valve leaflets so that they prolapse into the left atrium, often causing mitral regurgitation. "The objective of this work was to investigate the role of ZFP36 in mitral valve prolapse (MVP)." (PMID 41214760, 2025).
osteoporosis (1 paper, 2025). A condition of reduced bone mass, with decreased cortical thickness and a decrease in the number and size of the trabeculae of cancellous bone (but normal chemical composition), resulting in increased fracture incidence. "This study identified PDPK1, MAP1LC3B, ZFP36, DRAM1, and MPO as potential biomarkers and proposes a nomogram based on hub genes for predicting osteoporosis risk." (PMID 39791175, 2025).
Pan (1 paper, 2023). "Similar observations were made analyzing TCGA-Pan Cancer data and it was determined that positive correlations of TTP/ZFP36 expression with those stem-like markers were more significant in primary tumors (all subtypes considered) than in normal tissue." (PMID 38274271, 2023).
prostate adenocarcinoma (1 paper, 2024). "Loss of Zfp36 accelerates disease progression in a mouse model of prostate adenocarcinoma driven by Pten deletion." (PMID 39560993, 2024). "To model the clinical finding that low expression of ZFP36 synergizes with PTEN loss to drive aggressive PCa progression, we engineered Zfp36 deletion in a previously characterized mouse model of prostate adenocarcinoma induced by Pten deletion." (PMID 39560993, 2024). "Additionally, loss of ZFP36 in normal epithelial cells results in cell transformation substantial enough to develop prostatic hyperplasia and PIN, a precursor to prostate adenocarcinoma." (PMID 39560993, 2024).
prostate tumors (1 paper, 2024). "To examine the clinical response of ZFP36/TTP to treatment with enzalutamide (a nonsteroidal anti-androgen therapy), we examined 2 clinical cohorts where the prostate tumors from the same patient were investigated before and after enzalutamide treatment." (PMID 39560993, 2024).
prostatic intraepithelial neoplasia (1 paper, 2024). "Engineering prostate-specific Zfp36 deletion in vivo induced prostatic intraepithelial neoplasia, and, with Pten codeletion, resulted in rapid progression to castration-resistant adenocarcinoma." (PMID 39560993, 2024).
skin tumor (1 paper, 2021). "It would therefore be important to define the mechanisms leading to decreased ZFP36, ZFP36L1, and ZFP36L2 expression during skin tumor progression." (PMID 33497366, 2021).
synovitis (1 paper, 2023). Inflammation of a synovial membrane. "Third, the underlying regulatory and downstream mechanisms of JUN and ZFP36 in synovitis require further studies." (PMID 37741987, 2023). "The lower transcript levels of JUN and ZFP36 were predicted and validated in OA-associated synovitis, and this approach has high diagnostic efficacy for OA-associated synovitis." (PMID 37741987, 2023). "Two genes, i.e., JUN and ZFP36, were identified by screening the DEGs associated with synovitis." (PMID 37741987, 2023). "The ROC curve analysis suggested that JUN and ZFP36 expression has a predictive value in the development of synovitis during the OA process, with the maximum AUC value reaching 0.78 and 0.74, respectively." (PMID 37741987, 2023).
upper tract urothelial carcinoma (1 paper, 2022). "High loads of mutations in ZFP36—another member of the ZFP family—were associated with upper tract urothelial carcinoma." (PMID 35626146, 2022).
viral myocarditis (1 paper, 2025). Myocarditis that is caused by an infection with a viral agent. "Recent research indicates that Zfp36 plays a role in the regulation of ferroptosis, suggesting that Zfp36‐dependent ferroptosis could serve as a potential therapeutic target for viral myocarditis." (PMID 40000392, 2025).